TNF (tumor necrosis factor)
Diseases named in the same sentence as TNF in open-access papers (continued):
Sharing a sentence is not in itself a finding about the gene and the disease.
acute kidney injury (continued). "Thus, large-scale trials in severe alcoholic hepatitis showed that anti-TNF approaches (e.g., pentoxifylline) might not work in patients with severe disease and liver failure, but had positive effects in the presence of renal failure." (PMID 30941129, 2019). "Relevantly, the functional involvement of TNF-α in the pathogenesis of cisplatin-induced acute renal failure was determined in mice treated with cisplatin in the presence or absence of TNF-α production inhibitors, as well as in TNF-α knockout mice." (PMID 26881219, 2016). "Finally, in an LPS-induced acute kidney injury (AKI) model, MLN4924 attenuates renal inflammation by inactivating CRL1 and subsequent NFκB inactivation, leading to reduced production of pro-inflammatory cytokines (TNF-α, IL-6, and IL-1β) upon LPS stimulation in renal tubular cells." (PMID 38434245, 2023). "One SAE of renal failure was reported in the ETN treatment group, and one SAE of abnormal blood count was reported in the IFX treatment group; neither event was considered to be related to TNF inhibitor treatment." (PMID 28448562, 2017).
rheumatic diseases (235 papers, 2005 to 2026). "IL-6 and TNF-α are central cytokines in chronic low-grade inflammation and have been linked to functional decline and frailty in rheumatic diseases." (PMID 41488632, 2025). "MAS is a form of HLH seen in rheumatic disorders, caused by dysregulated immune activation and excessive cytokine production (IL-1β, TNF, IFN-γ), leading to hyperinflammation and tissue damage." (PMID 40385895, 2025). "In a population-based study conducted in Brazil, a country with a high incidence of TB, researchers reported an increased risk of TB associated with the use of TNF-α inhibitors in patients with rheumatic diseases." (PMID 38674225, 2024). "Biologic/targeted synthetic treatment changed the treatment of several rheumatic diseases in the early 2000s, but it was associated with increased mycobacterial infections, especially in TNF-α-targeted therapy users." (PMID 39661841, 2024). "TNF-α is associated with inflammatory and destructive processes and has been shown to be one of the most important pro-inflammatory cytokines in rheumatic diseases and—possibly—in SLE." (PMID 37554366, 2023). "Monotherapy of anti‐TNF in rheumatic disease has been associated with a lower rate of hospital admission for COVID‐19 patients." (PMID 37382255, 2023). "Not only IL-1β but also TNF-α and IL-6, which are associated with migraine, as pointed out in this review, have already been established for clinical application in rheumatic diseases." (PMID 37176049, 2023). "Human studies demonstrated that patients with rheumatic disease using TNF-α antagonists had an increased risk of ATB and LTBI reactivation, suggesting that TNF-α is a key factor in controlling MTB invasion and proliferation." (PMID 34225667, 2021). "Passive immunization aimed at neutralizing the pathogenic cytokines such as TNF-α and IL-6 with monoclonal antibodies (mAbs) or soluble receptors has been proven to be an effective therapy strategy of rheumatic diseases such as RA and AS." (PMID 32258176, 2020). "A follow-up study found that individuals with rheumatic disease who took >/= 10 mg/day of Prednisone were more likely to be hospitalized, whereas individuals with rheumatic disease who took TNFα were at a decreased risk of hospitalization." (PMID 33193418, 2020). "Rheumatic disorders are associated with overexpression of the pro inflammatory cytokine (TNFα), and these disorders respond to treatment with TNF inhibitors (TNFi)." (PMID 32494263, 2020). "In the treatment of rheumatic diseases, anti-TNF-α therapy increases susceptibility to TB reactivation." (PMID 33105734, 2020). "MA affects the production of tumor necrosis factor-a (TNF-a), a type of cytokine which causes rheumatism." (PMID 29558490, 2018). "TNF-α inhibitors used for the treatment of rheumatic diseases can increase the risk of frank toxoplasmosis; therefore, screening for latent T. gondii infection is strongly recommended before initiating such therapy." (PMID 29065914, 2017). "This would explain why patients with rheumatic diseases treated with an anti-TNF-α inhibitor have an increased risk of activation and dissemination of latent tuberculosis." (PMID 26273486, 2015). "TNF-α antagonists are generally considered to have a favorable benefit/risk ratio, and considered indispensable for treatment of patients with rheumatic diseases." (PMID 26474294, 2015). "Additionally, anti-TNF-α therapy, commonly used in the treatment of rheumatological disorders, has been associated with unexpected demyelinating events." (PMID 37483590, 2023). "As for the patients who need to use biological drugs such as anti-TNF agents for rheumatic disease, treatment may be delayed due to the risk of infection." (PMID 36422487, 2022). "The results indicated that IL-33 polymorphisms might be associated with rheumatic disease risk and anti-TNF treatment outcomes in Caucasians." (PMID 34177886, 2021).
rheumatic diseases (continued). "For example, deletion of TNF from macrophages is associated with lower plasma creatinine and albuminuria in murine diabetic nephropathy; of note, three TNF blockers have been approved for clinical treatment of rheumatic diseases." (PMID 32660446, 2020). "Consequently, uncontrolled production or function of TNF has been associated to the pathology of several rheumatic diseases, including r-axSpA." (PMID 32303225, 2020). "In summary, anti-TNF-α treatment seems to increase the risk of exacerbation of WD and WD may mimic a rheumatic disease." (PMID 26215452, 2015). "In addition, anti-TNF therapies has been associated with a more severe course of HZ among patients with rheumatic diseases; those receiving anti-TNF therapies were 9 times more likely than those not to be hospitalized for HZ." (PMID 22024532, 2011). "Stress cytokines tumor necrosis factor α, interleukin-1 β and interleukin-6 modulate the activity of a variety of cell types including osteoblasts, and are involved in the pathogenesis of several rheumatic diseases associated with systemic bone loss." (PMID 23675187, 2010). "However, serious infections are a major concern in patients with rheumatic diseases, and inhibition of TNF-α increases the risk of serious and benign infections." (PMID 20633267, 2010). "However, TNF antagonists decreased the risk of hospitalization in patients with rheumatic disease." (PMID 36134550, 2022). "Also, the underlying disease process in rheumatic disease may further complicate our ability to determine any relationship in between anti-TNF and malignancy risk." (PMID 29540190, 2018). "This retrospective study included 261 children with a rheumatic disease who were treated with TNF-α inhibitors and followed up on a fixed schedule between January 2018 and December 2022." (PMID 42141213, 2026). "TNF-α levels were higher in patients with AS and anti-TNF therapy than in subjects without AS, which is different from what has been reported on rheumatic diseases with anti-TNF therapy." (PMID 40981186, 2025). "Presented TNF-related mechanisms contribute to acute and chronic muscle damage; however, anti-TNF therapies, effective in other inflammatory and rheumatic diseases, have shown limited benefits in IIM21,22." (PMID 41272109, 2025). "Proinflammatory cytokines, including tumor necrosis factor-alpha (TNF-α), interleukin-6 (IL-6), and interleukin-17 (IL-17), are elevated in rheumatic disorders due to persistent inflammation." (PMID 40937212, 2025). "Collectively, these results suggested that the effect of TG on the TNF‐a‐induced rheumatism cell model was impeded by Lnc‐ENST00000602558, as indicated increased IGF1 levels and the induced production of pro‐inflammatory cytokines." (PMID 38270302, 2024). "Proinflammatory cytokines such as TNFα (tumor necrosis factor alpha), IL-6 (interleukin 6) and IL-1β (interleukin 1 beta), which circulate in the systemic blood flow in rheumatic diseases, influence the brain structures." (PMID 39845811, 2024). "In the field of rheumatic disease, it has been shown that even small amounts of IL-12 can induce the production of proinflammatory cytokines, including IL-1 and TNF-α." (PMID 38675400, 2024). "In recent years, anti-TNF drugs that antagonize the biological activities of TNF-α have been successfully used to treat rheumatic disorders." (PMID 39734351, 2024). "A similar approach is maintained regarding latent tuberculosis testing before beginning anti-TNF-α therapy for rheumatic diseases." (PMID 39310504, 2024). "It is evident that several rheumatic diseases display elevated serum levels of inflammatory cytokines, such as IL-2, IL-6, TNF-α and markers of systemic inflammation." (PMID 37681925, 2023). "Cytokines (tumor necrosis factor α (TNF-α), various interleukins), activated T cells, and B cells are associated with the development of rheumatic diseases and provide a target for biologic therapy." (PMID 37623450, 2023).
rheumatic diseases (continued). "In this line, several studies have revealed that curcuminoids act to inhibit the expression of IL-1, IL-8, and IL-6, and TNF-α, thereby decreasing the severity of rheumatic disease." (PMID 37521415, 2023). "TNF-α induces the proliferation of HUVECs and the formation of new blood vessels, which play key roles in cancer and rheumatic disease, and blocking TNF-α can significantly inhibit angiogenesis, tumor growth, and metastasis in vivo." (PMID 37511521, 2023). "Another study followed HIV-positive patients with rheumatic disease using TNF inhibitors, between 2003 and 2021, and observed that in general, these drugs did not cause serious infectious episodes, being considered relatively safe even in the long term." (PMID 36979909, 2023). "It is important to remember that anti-TNFα therapy represents the leading treatment for rheumatic diseases." (PMID 36902036, 2023). "Golimumab, a monoclonal antibody against tumor necrosis factor–α (TNF-α), is used widely for treatment of rheumatic diseases." (PMID 37751000, 2023). "Tumor necrosis factor-α antagonists have been the most effective tool for controlling patients suffering from a variety of rheumatic diseases over the last two decades." (PMID 37332933, 2023). "Previous studies had linked IL-15 production with TNF-α stimulation of secreting cells, and TNF-α-targeted therapies have been shown to reduce serum IL-15 levels in patients with rheumatic diseases." (PMID 36009415, 2022). "Eczematous eruptions have been reported after the use of TNF-α inhibitors for various rheumatic diseases." (PMID 35884790, 2022). "Inhibition on TNF-α and IL-1β has been demonstrated to reduce neutrophil infiltration and pain in rheumatic disease." (PMID 34586567, 2022). "Another prospective study, which included 150 patients with rheumatic diseases that were treated with TNF-α inhibitors, demonstrated that 8 patients developed eczematous eruptions." (PMID 35884790, 2022). "Kameda reported that the TNF-alpha levels in IPAF patients were higher than in the IPF group and lower than in patients with collagen vascular diseases–associated interstitial lung disease (CVD-ILD), however, without statistical significance." (PMID 35011819, 2021). "On the other hand, several researchers have reported that females were less likely to respond to anti-TNF treatment and were more likely to discontinue anti-TNF treatment early based on data from registries of rheumatic disease including AS." (PMID 33541326, 2021). "Tumor necrosis factor inhibitors (TNF inhibitors) were the first bDMARDs to be developed for rheumatic diseases and are currently most frequently prescribed after an inadequate response to conventional synthetic (cs)DMARDs." (PMID 33415451, 2021). "Experience from the biologic usage in adult rheumatic diseases has shown higher chances of TB reactivation with anti TNF agents." (PMID 35128322, 2021). "Tumor necrosis factor inhibitors (TNFi) have significantly improved treatment outcome of rheumatic diseases since their incorporation into treatment protocols two decades ago." (PMID 32174918, 2020). "Few other studies in the Arab region have assessed the efficacy of anti-TNF-α drugs including infliximab in treating several rheumatic diseases." (PMID 33521572, 2020). "The inflammatory process of rheumatism is determined by the secretion of proinflammatory cytokines such as tumor necrosis factor (TNF-α) and interleukin (IL-1) into the synovial cavity." (PMID 33374575, 2020). "In patients with rheumatic disease, levels of the systemic inflammatory factor TNF-α play an important role in occurrence and development of disease." (PMID 31506454, 2019). "Six patients were receiving TNF-α inhibitors only, and 10 patients (all with rheumatic disease) had additional treatment with methotrexate (5 patients), leflunomide (3 patients), methylprednisolone (1 patient) or meloxicam (1 patient)." (PMID 31684103, 2019).
rheumatic diseases (continued). "TNF is a crucial cytokine for the pathogenesis of several rheumatic diseases, and its inhibition is a mainstay of treatment to control joint symptoms, including pain." (PMID 32038637, 2019). "The benefit of anti-tumor necrosis factor (TNF) in refractory rheumatic disease is well established." (PMID 29540190, 2018). "Anti-TNF (Tumor necrosis factor) therapy is effective in treating pediatric patients with refractory rheumatic disease." (PMID 29540190, 2018). "Introduction of anti-tumor necrosis factor alpha (anti-TNFα) therapy for rheumatic disease has revolutionized disease control and greatly improved the outcome of rheumatic disease." (PMID 30043213, 2018). "This suggests that expression of circulating miRNA-5196 from patients suffering from rheumatic diseases including SSc, RA and AS is significantly elevated and it can be reduced by anti-TNF-α treatment." (PMID 29744553, 2018). "In this study, we describe six children with rheumatic disease who developed one or more neoplasms during or following exposure to anti-TNF treatment at our centre." (PMID 29540190, 2018). "Among our confirmed cases were Swedish patients with TNFα modulating therapy for rheumatic disease infected with leishmaniasis while visiting a treatment clinic in Spain." (PMID 29848389, 2018). "For clinical practice, it is very important to mention other studies showing high expression of TNFα not only in serum and in joints involved in these rheumatic diseases but also in aqueous humor in patients with HLA-B27-associated AAU." (PMID 30206554, 2018). "Adiponectin the second adipokine most evaluated in rheumatic diseases possesses a complex role with some anti-inflammatory effects as well as inhibition of TNF-α and IL-6 production and the induction of IL-10 synthesis." (PMID 28898254, 2017). "This issue was addressed in a prospective study of patients with rheumatic diseases before receiving TNF-α blockers." (PMID 28337644, 2017). "Anti-tumor necrosis factor (TNF) agents have emerged as the treatment of choice in many rheumatic diseases, primarily aggressive forms of RA." (PMID 28146077, 2017). "The role of excess TNF-α has been studied in many rheumatic diseases leading to the development of multiple agents directed against this inflammatory cytokine." (PMID 29721512, 2017). "The use of TNF antagonists in combination with MTX is approved for multiple rheumatologic disorders." (PMID 28492015, 2016). "A previous cohort study of 631 patients with rheumatic diseases showed that patients with indeterminate results were more likely with SLE using a tumor necrosis factor (TNF)-α inhibitor." (PMID 27755587, 2016). "Tumor necrosis factor-alpha (TNF-α) plays a key role in the pathogenesis of many chronic inflammatory and rheumatic diseases, including AS." (PMID 25764452, 2015). "Larger prospective studies are necessary to better understand not only TB reactivation rates, but also IGRA reversion and conversion in patients with rheumatic diseases during TNF-α antagonist therapy." (PMID 26474294, 2015). "In China, anti-TNF-α therapy is widely applied as treatment for various rheumatic diseases due to its clinical efficacy." (PMID 25764452, 2015). "According to our current protocol using QFT-GIT with supplementary TST results, the prevalence of LTBI patients with rheumatic diseases before starting TNF-α antagonist therapy was 29.5% (46/156) at the initial screening." (PMID 26474294, 2015). "This is especially the case with TNF-α inhibitors, which are also used for other diseases such as rheumatic diseases." (PMID 26475276, 2015). "Before starting TNF-α antagonist therapy, 156 consecutive patients with rheumatic diseases were screened for LTBI using QFT-GIT and T-SPOT.TB tests." (PMID 26474294, 2015). "Reactivation of latent tuberculosis infection (LTBI) is one of the major complications of tumor necrosis factor (TNF)-α antagonist therapy in patients with rheumatic diseases." (PMID 26474294, 2015).